TAGLN3 (transgelin 3)
Synonyms: NP22; NP25; NP24
Tractability: PROTAC: its protein half-life has been measured.
Gene: Protein-coding gene on chromosome 3 (111,998,739 to 112,013,888, forward strand). Ensembl gene ENSG00000144834.
Gene Ontology:
Molecular function: protein binding; actin filament binding
Biological process: actin filament organization; central nervous system development
Cellular component: actin cytoskeleton; nucleus; synapse
Genetic constraint (gnomAD): Loss-of-function variants: 12 observed, 26.25 expected, observed/expected ratio (o/e) 0.46, 90% interval 0.29 to 0.74. The upper end of that interval is the gene's LOEUF score, 0.74, which puts it in group 3 of 6, group 1 being the genes least tolerant of losing a copy. Missense variants: 218 observed, 271.89 expected, observed/expected ratio (o/e) 0.8, 90% interval 0.72 to 0.9. Synonymous variants: 96 observed, 101.57 expected, observed/expected ratio (o/e) 0.95, 90% interval 0.8 to 1.12.
Homologues: Orthologues: guinea pig TAGLN3 (99% identical), mouse Tagln3 (99% identical), rat Tagln3 (99% identical), dog TAGLN3 (98% identical), macaque TAGLN3 (96% identical), rabbit TAGLN3 (96% identical), chimpanzee TAGLN3 (95% identical), pig TAGLN3 (95% identical), zebrafish tagln3a (76% identical), Drosophila melanogaster Chd64 (43% identical), Caenorhabditis elegans cpn-2 (41% identical), Drosophila melanogaster Mp20 (39% identical), and 3 more. Paralogues in human: TAGLN2 (69% identical), TAGLN (67% identical), CNN3 (45% identical), CNN1 (43% identical), CNN2 (42% identical).
Diseases named in the same sentence as TAGLN3 in open-access papers:
TAGLN3 is named in the same sentence as 13 diseases in open-access papers, as found by Europe PMC text mining. Sharing a sentence is not in itself a finding about the gene and the disease. The quoted sentences say what the papers report.
schizophrenia (2 papers, 2018 to 2021). A major psychotic disorder characterized by abnormalities in the perception or expression of reality. "TAGLN3 encodes a cytoskeleton-associated protein and is reported to possess an association with schizophrenia." (PMID 35047024, 2021).
alcoholism (1 paper, 2016). "Transgelin-3 (also known as neuronal protein 22, NP22, or NP25) is specifically expressed in brain tissue and is upregulated in the superior frontal cortex and hippocampus in alcoholic humans and rat models of alcoholism." (PMID 27232882, 2016).
bladder cancer (1 paper, 2016). "TAGLN2, which is homologous gene of TAGLN3, was reported to have tumour-suppressive function in bladder cancer." (PMID 27586240, 2016).
colorectal cancer (1 paper, 2021). A primary or metastatic malignant neoplasm that affects the colon or rectum. "Interestingly, TAGLN2 elevated expression has been associated with progression of colorectal cancer; (c) TAGLN3 (also known as NP22 or NP25) is predominantly expressed in the nervous system." (PMID 34322481, 2021).
COVID-19 (1 paper, 2023). A disease caused by infection with severe acute respiratory syndrome coronavirus 2. "Five hub genes, including GAD2, SST, TAGLN3, SYP, and KCNJ4, were further verified using the test_datasets of COVID-19, AD, and PD." (PMID 36902271, 2023).
epilepsy (1 paper, 2021). A brain disorder characterized by episodes of abnormally increased neuronal discharge resulting in transient episodes of sensory or motor neurological dysfunction, or psychic dysfunction. "Higher expression levels were observed for ADPRC, calreticulin, LPAR3 and transgelin 3 across the 3 rat models of epilepsy." (PMID 33859251, 2021). "An increase in transgelin 3 expression level was seen on the both hippocampi across the 3 rat models of epilepsy with different fold." (PMID 33859251, 2021).
glioma (1 paper, 2016). A benign or malignant brain and spinal cord tumor that arises from glial cells (astrocytes, oligodendrocytes, ependymal cells). "TAGLN3 might be another important role in promoting glioma progression which leads to worse prognosis." (PMID 27586240, 2016).
cancer (2 papers, 2011 to 2018). A tumor composed of atypical neoplastic, often pleomorphic cells that invade other tissues. "TAGLN and TAGLN3 are homologues of TAGLN2, and TAGLN3 is a novel neuron-specific protein and has not been reported in cancer." (PMID 21304530, 2011).
TAGLN3 also shares sentences with these, for which no sentence is quoted: tumor (2 papers); Alzheimer disease (1); breast carcinoma (1); leiomyosarcoma (1); Parkinson disease (1).